TNIP1 (TNFAIP3 interacting protein 1)
Diseases named in the same sentence as TNIP1 in open-access papers (continued):
Sharing a sentence is not in itself a finding about the gene and the disease.
glioblastoma (3 papers, 2017 to 2021). The most malignant astrocytic tumor (WHO grade IV). "To further verify the high TNIP1 levels in glioma tissue, we collected 20 glioblastoma samples and examined the expression of TNIP1 by immunohistochemical, immunoblot and quantitative polymerase chain reaction (qPCR) analyses." (PMID 31691497, 2020). "Glioblastoma patients with the highest TNIP1 levels among the three types of glioma exhibited the poorest survival (less than 60 months) in both the high and low TNIP1 level groups." (PMID 31691497, 2020). "The Rembrandt data showed considerable increases in TNIP1 mRNA levels in different types of glioma tissue, including glioblastoma, oligodendroglioma and astrocytoma, compared with normal brain tissue." (PMID 31691497, 2020). "Compared to the pericarcinomatous tissue, enhanced expression of TNIP1 was detected in glioblastoma tissue." (PMID 31691497, 2020). "Interestingly, glioma patients with high TNIP1 levels in all neoplasm tissues, including glioblastoma, oligodendroglioma and astrocytoma, showed significantly shorter survival compared with glioma patients with low TNIP1 levels." (PMID 31691497, 2020). "Because TNIP1 is involved in NF‐κB signalling in multiple immune diseases, we investigated several TNF‐α/NF‐κB signalling members in glioblastomas." (PMID 31691497, 2020). "As expected, TNIP1 complex components A20 and IKK were highly expressed in glioblastoma tissue." (PMID 31691497, 2020). "In addition, TNIP1 signalling cascade components, including TNF‐α, TNF receptor and three IκB subunits, were significantly up‐regulated in glioblastoma tissue compared with normal brain tissue." (PMID 31691497, 2020). "To determine whether deregulation of negative regulators of NF-κB has a role in constitutive NF-κB activation in glioblastoma, we analyzed expressions of the NF-κB regulators NFKBIA, TNFAIP3, TNIP1 and TNIP2 in glioblastoma patients from The Cancer Genome Atlas (TCGA)." (PMID 28166199, 2017).
nephritis (3 papers, 2021 to 2024). Inflammation of renal tissue. "Macrophage-specific Tnip1 deletion is sufficient for nephritis to develop in Tnip1-/- mice, and high levels of TLR7 were expressed in patrolling monocytes of NZBWF1 mice." (PMID 34868046, 2021).
pustular psoriasis (3 papers, 2021 to 2025). "Other genes with mutations associated with pustular psoriasis include caspase-activating recruitment domain member 14 (CARD14), adaptor protein complex 1 subunit sigma 3 (AP1S3), TNFAIP3-interacting protein 1 (TNIP1), and serpin family A member 3 (SERPINA 3)." (PMID 33919434, 2021). "Other genes involved in pustular psoriasis are SERPINA1 and SERPINA3 (serine protease inhibitors that inhibit cathepsin G, neutrophil elastase, and proteinase 3), TNIP1 and IL1RN." (PMID 37628670, 2023).
acne (2 papers, 2018 to 2023). An inflammatory process of the sebaceous glands which is characterized by comedones, nodules, papules and/or pustules on the skin. "Development of novel, well-tolerated, TNIP1-specific acne therapeutic modalities could potentially reduce inflammation without the harmful side effects of currently available treatment options (antibiotic, retinoid or hormonal formulation usage)." (PMID 30319618, 2018). "Since ATRA is an effective drug used for acne treatment, we examined whether this compound is capable of regulating TNIP1 and, thus, the expression of downstream targets of the TLR signaling pathway in keratinocytes." (PMID 30319618, 2018). "In this experimental system, all-trans retinoic acid (ATRA), a known acne treatment, was found to upregulate TNIP1 expression in agreement with our previous findings of ATRA regulation of the TNIP1 promoter." (PMID 37569318, 2023). "Based on these findings, we propose that ATRA may exhibit dual effects in acne therapy by both affecting the expression of the negative regulator TNIP1 and attenuating TLR2-induced inflammation." (PMID 30319618, 2018).
Arthritis (2 papers, 2011 to 2014). Inflammation of a joint. "Through stratified analysis, TNFAIP3 and ETS1 showed significant associations with multiple SLE subphenotypes (such as malar rash, arthritis, hematologic disorder and antinuclear antibody) while TNIP1 just showed relatively weak association with onset age." (PMID 22087647, 2011).
asthma (2 papers, 2014 to 2020). "Polymorphisms in the A20 gene locus or its binding partner TNIP1 are significantly associated with a number of human inflammatory and autoimmune conditions and in case of TNIP1 also with asthma." (PMID 24453940, 2014).
diabetes (2 papers, 2023 to 2024). "Consequently, we speculated that FTO causes retinal vascular endothelial dysfunction in diabetes possibly through the RNA demethylation of Tnip1." (PMID 37781923, 2023). "In the present study, TNIP1-NF-κB–mediated endothelial inflammation in diabetes was regulated by FTO." (PMID 37781923, 2023). "In this study, sustained expression of Tnip1 using an AAV vector attenuated diabetes-induced vascular dysfunction in vivo, demonstrating its therapeutic potential for the management of diabetes-associated vascular complications." (PMID 37781923, 2023). "Tnip1, with most remarkably reduced levels of mRNA and m6A peaks, was identified as the target of m6A modifications stressed by diabetes." (PMID 37781923, 2023). "FTO-mediated RNA demethylation of TNIP1 activates NF-κB, thus accelerating diabetes-induced vascular endothelial dysfunction." (PMID 37781923, 2023). "To delineate the regulation of the NF-κB pathway by TNIP1 in diabetes, as TNIP1 is an A20 binding protein, we first used a coimmunoprecipitation assay in HRMECs to detect the direct interaction among TNIP1, A20, and IKKγ." (PMID 37781923, 2023). "Our findings indicated that, in diabetes, TNIP1 physically links A20 to IKKγ and facilitates A20-mediated deubiquitination of IKKγ, thus resulting in the suppression of NF-κB." (PMID 37781923, 2023). "The results revealed upregulated FTO, accompanied by decreased TNIP1 and elevated NF-κB (p105/p50) levels in EC Ftofl/fl mice with diabetes, whereas in EC FtoΔ/Δ mice, upregulated TNIP1 with suppressed NF-κB was observed." (PMID 37781923, 2023). "Collectively, these results indicate that TNIP1 attenuates diabetes-related retinal vascular dysfunction and inflammation both in vivo and in vitro." (PMID 37781923, 2023). "We further determined the effect of TNIP1 on diabetes-induced retinal vascular dysfunction." (PMID 37781923, 2023). "TNIP1 alleviates diabetes-induced retinal vascular endothelial dysfunction." (PMID 37781923, 2023). "Tnip1 had the most significant reduction in both m6A peaks and mRNA levels in diabetes." (PMID 37781923, 2023). "In diabetes, excessive FTO downregulates TNIP1, a central regulator of inflammation, thereby activating NF-κB and subsequently increasing inflammatory cytokines (IL-1β and IL-18) in an m6A-dependent manner, ultimately leading to vascular endothelial dysfunction." (PMID 37781923, 2023).
esophageal cancer (2 papers, 2015 to 2017). A primary or metastatic malignant neoplasm involving the esophagus. "This case-control study was designed to investigate whether genetic variants of NAF1 and TNIP1 were associated with the risk of esophageal cancer in the Han Chinese population." (PMID 28454086, 2017). "We investigated whether single nucleotide polymorphisms (SNPs) in the nuclear assembly factor 1 (NAF1) and TNFAIP3-interacting protein 1 (TNIP1) gene were associated with susceptibility to esophageal cancer in a Chinese Han population." (PMID 28454086, 2017). "A previous study revealed that TNIP1 inhibited the activation of nuclear factor kappa-B (NF-κB), and another study demonstrated that blocking the NF-κB signaling pathway inhibited esophageal cancer proliferation and metastasis." (PMID 28454086, 2017). "Given the importance of telomere length and the NF-κB signaling pathway in the development and maintenance of esophageal cancer, we hypothesized genetic polymorphisms in NAF1 and TNIP1 may influence esophageal cancer susceptibility." (PMID 28454086, 2017).
gastric carcinoma (2 papers, 2016 to 2020). A carcinoma that arises from epithelial cells of the stomach. "Our results are the first to suggest that genetic variation in TNIP1 gene is associated with gastric carcinoma, though, this finding must be confirmed in other populations with larger sample size." (PMID 27250029, 2016). "Conversely, the haplotype “CT” of TNIP1 (rs7708392-rs10036748) may act as a genetic protective factor for gastric carcinoma (adjusted OR= 0.731, 95%CI: 0.552-0.970, P= 0.030)." (PMID 27250029, 2016). "To assess the association between four TNIP1 SNPs (rs3792792, rs4958881, rs7708392, rs10036748) and carcinogenesis, we used Sequenom Mass-ARRAY technology to determine the genotypes of 302 gastric carcinoma patients and 300 healthy controls in a Northwest Chinese Han population." (PMID 27250029, 2016).
glioma (2 papers, 2019 to 2020). A benign or malignant brain and spinal cord tumor that arises from glial cells (astrocytes, oligodendrocytes, ependymal cells). "In TNIP1‐down‐regulated glioma cells, loss of TNIP1 prevented the formation of the A20 complex and IKK was released from ubiquitin binding of the A20 complex." (PMID 31691497, 2020). "Furthermore, loss of TNIP1 disbanded the A20 complex responsible for IκB degradation and NF‐κB nucleus translocation, and consequently erased TNFα‐induced glioma cell proliferation." (PMID 31691497, 2020). "In summary, high levels of TNIP1 in normal glioma cells supported the formation of the A20 complex, which freed IκB and led to inhibitive binding to NF‐κB." (PMID 31691497, 2020). "To evaluate the role of TNIP1 in glioma cell proliferation, we established stable TNIP1‐interfered U251 glioma cells." (PMID 31691497, 2020). "Down‐regulation of TNIP1 dramatically retarded glioma cell proliferation (TNIP1‐sh3: P < .01; TNIP1‐sh4: P < .05) compared with the control cells." (PMID 31691497, 2020). "Flow cytometry further demonstrated that TNIP1‐interfered glioma cells (TNIP1‐sh3) were arrested at the G0/G1 phase (P < .001) and resisted entry into the G2/M phase (P < .001) compared with the vector control." (PMID 31691497, 2020). "Our work revealed high levels of TNIP1 and its binding proteins, including A20 and IK, in glioma tissue, with its expression found to be negatively related to survival of glioma patients." (PMID 31691497, 2020). "Molecular and cellular study illustrated that down‐regulation of TNIP1 significantly damaged cell proliferation of glioma cells." (PMID 31691497, 2020). "From day 5 after seeding, TNIP1‐interfered glioma cell lines (TNIP1‐sh3 and TNIP1‐sh4) showed distinct proliferation curves." (PMID 31691497, 2020). "In consideration of this possibility, we treated TNIP1‐interfered glioma cells with the same concentration of TNF‐α and same time course." (PMID 31691497, 2020). "Here, we report that high levels of TNIP1 show a positive correlation with glioma cell proliferation and poor survival in glioma patients." (PMID 31691497, 2020). "H&E staining and immunohistochemical analysis confirmed the presence of neoplastic cells and TNIP1 expression in glioma xenografts of vector control cells (left pane)." (PMID 31691497, 2020). "We applied an orthotopic glioma xenograft strategy to explore the effect of TNIP1 down‐regulation on glioma tumour initiation and progression." (PMID 31691497, 2020). "To identify the correlation between TNIP1 expression and glioma progression, we determined the mRNA level of TNIP1 in glioma specimens." (PMID 31691497, 2020). "Down‐regulation of TNIP1 decreased glioma cell proliferation, in which the TNF‐α/NF‐κB signalling pathway was involved." (PMID 31691497, 2020). "Collectively, our study showed high levels of TNIP1 in glioma tissue, which were further correlated with poor survival in glioma patients." (PMID 31691497, 2020). "This suggests that TNIP1 is a key regulator in the TNF‐α signalling pathway in glioma tissue." (PMID 31691497, 2020). "Thus, our investigation uncovered a vital function of the TNIP1‐mediated TNF‐α/NF‐κB axis in glioma cell proliferation and provides novel insight into glioma pathology and diagnosis." (PMID 31691497, 2020). "Therefore, this study provides direct experimental evidence of the relevance of TNIP1 in glioma progression." (PMID 31691497, 2020). "High TNIP1 levels in glioma tissue were also observed in the Lee brain and Sun brain data." (PMID 31691497, 2020). "We also established stable TNIP1‐overexpressed U251 glioma cells." (PMID 31691497, 2020). "Furthermore, RNA interference with TNIP1 expression in glioma cells markedly impacted proliferation activity." (PMID 31691497, 2020). "In addition, TNIP1‐RNA interference decreased the phosphorylation and degradation of IκB‐α in glioma cells." (PMID 31691497, 2020).
glioma (continued). "In addition, whether TNIP1 regulates the NF‐κB signalling pathway via ubiquitin binding and which domain(s) are responsible for this regulation in glioma cells are unclear." (PMID 31691497, 2020). "Here, we revealed high levels of TNIP1 and TNF‐α/NF‐κB in glioma tissue." (PMID 31691497, 2020). "TNF‐α treatment elevated proliferation activity through NF‐κB signalling in normal glioma cells, but not in TNIP1‐down‐regulated glioma cells." (PMID 31691497, 2020). "Thus, our investigation demonstrated that TNIP1 is an essential component for TNF‐α–induced phosphorylation and degradation of IκB‐α regulates glioma cell fate." (PMID 31691497, 2020). "Therefore, we supposed that TNF‐α signalling induced the formation of a complex comprised of A20, TNIP1 and IKK, and this complex phosphorylated and induced IκB‐α degradation, leading to liberation of NF‐κB from the inhibitive condition in normal glioma cells." (PMID 31691497, 2020). "Although TNIP1 and the TNF‐α/NF‐κB axis play key roles in immune diseases and inflammatory responses, their relationship and role in glioma remain unknown." (PMID 31691497, 2020). "However, TNIP1 overexpression did not significantly increase P65 and IκB‐α phosphorylation in glioma cells." (PMID 31691497, 2020).
AIDS (1 paper, 2025). A syndrome resulting from the acquired deficiency of cellular immunity caused by the human immunodeficiency virus (HIV). "Several top-ranking genes, including BLK, STAT4, and TNIP1, have been previously implicated in SjD and other AIDs, validating our approach." (PMID 40429780, 2025).
Alzheimer disease (1 paper, 2025). A progressive, neurodegenerative disease characterized by loss of function and death of nerve cells in several areas of the brain leading to loss of cognitive function such as memory and language. "In this study, we identified known ADRD loci located in SHARPIN and TNIP1, along with nine novel risk loci − including KCTD13 – that are shared between Alzheimer’s disease and hippocampal volume." (PMID 40787599, 2025).
ankylosing spondylitis (1 paper, 2019). An autoimmune chronic inflammatory disorder characterized by inflammation in the vertebral joints of the spine and sacroiliac joints. "This study was conducted to clarify the associations of tumor necrosis factor-α induced protein 3 (TNFAIP3) and TNFAIP3-interacting protein 1 (TNIP1) genetic polymorphisms with ankylosing spondylitis (AS) susceptibility." (PMID 31308453, 2019).
depression (1 paper, 2026). "Furthermore, the correlation between the pre-treatment expression levels of TNIP1 and its transcription factors with the degree of depression improvement indicated that lower pre-treatment levels of PPAR-γ were associated with better therapeutic outcomes in alleviating depression." (PMID 41479556, 2026).
diabetic retinopathy (1 paper, 2023). "To confirm the sequencing findings, we proved that the protein level of TNIP1 was decreased, accompanied by upregulated FTO, in the retinal fibrovascular membranes of the patients with diabetic retinopathy, diabetic murine retinas, and HRMECs treated with high glucose." (PMID 37781923, 2023).
Glucose intolerance (1 paper, 2026). Glucose intolerance (GI) can be defined as dysglycemia that comprises both prediabetes and diabetes. "The predictor variables can be considered in three groups: those with insulin and glucose intolerance (Mbd2, Tnip1, Itgb4, and Iffo2), those with BMR (1010001N08RiK and Clvs2), and those associated with Tb (Calb2)." (PMID 41432313, 2026).
myasthenia gravis (1 paper, 2021). Myasthenia gravis (MG) is a rare, clinically heterogeneous, autoimmune disorder of the neuromuscular junction characterized by fatigable weakness of voluntary muscles. "We identified several genes that were specifically linked to early onset myasthenia gravis including TNIP1, ORMDL3, GSDMB, and TRAF3." (PMID 34279044, 2021). "Findings from this study advance the knowledge gained through GWAS by providing functional evidence for previously implicated genes, such as TNIP1 and CLTA4 in EO and LO myasthenia gravis, respectively." (PMID 34279044, 2021).
Shock (1 paper, 2019). The state in which profound and widespread reduction of effective tissue perfusion leads first to reversible, and then if prolonged, to irreversible cellular injury. "When the TNFAIP3, TNIP1, and MyD88 SNPs were included in the model, only the TNFAIP3 rs6920220 and TNIP1 rs3792783 SNPs were selected, and the predictive value significantly improved for discriminating between survivors and nonsurvivors shortly after septic shock onset (the first 28 days)." (PMID 30813592, 2019).
Sjögren’s syndrome (1 paper, 2019). "In fact, the SNP rs73272842 has shown to be the most statistically significant expression quantitative trail loci (eQTL) among several TNIP1 SNPs in Sjogren’s syndrome patients." (PMID 30813592, 2019).
Type 1 Diabetes (1 paper, 2024). "We found GWAS links between 7 T2D-DMP genes and T2D or related phenotypes, including SPRED2 (T2D), ITPR1 and PLD6 (Diabetic complications), SLC16A3 (BMI), TCF7 (Type 1 Diabetes), RGL3 (blood pressure) and TNIP1 (autoimmune traits)." (PMID 38574408, 2024).
type 2 diabetes (1 paper, 2026). "Mbd2 and Tnip1 have significant relationships between DNAm variation and insulin type 2 diabetes." (PMID 41432313, 2026).
VKH syndrome (1 paper, 2014). "We also investigated the relationship between the clinical features of VKH syndrome patients and TNIP1 polymorphisms." (PMID 24788730, 2014). "Furthermore the association of the TNIP1 gene association with VKH syndrome was only performed in a Chinese Han population and further studies are needed in other ethnic populations." (PMID 24788730, 2014). "A TNIP1 polymorphism may be a risk factor for VKH syndrome in Han Chinese." (PMID 24788730, 2014). "The aim of the present study was to investigate the association of TNIP1 gene variants with the risk for BD and VKH syndrome, which to our knowledge, has not yet been reported." (PMID 24788730, 2014). "In this study we show an association between a TNIP1 rs17728338 gene polymorphism with VKH syndrome but not with BD." (PMID 24788730, 2014). "Analysis of extraocular clinical findings, did not reveal an association of the TNIP1 gene polymorphisms with BD or VKH syndrome subgroups." (PMID 24788730, 2014).
tumor (11 papers, 2016 to 2024). "As a result, we conclude that polymorphisms in the TNIP1 gene increase the possibility of developing neoplasms." (PMID 27250029, 2016). "Strikingly, for genes in cluster ii), which are specifically up-regulated in AAS, high expression of 7 of the top 10 genes (C3, CD74, HLA-DRA, STRA6, IGFBP4, PIGR, and TNIP1) was strongly associated with better cumulative survival than tumours with low expression of these genes." (PMID 32218455, 2020). "One more tumor harbored another previously undescribed RET fusion, TNIP1/RET." (PMID 34282777, 2021).